TFAM (transcription factor A, mitochondrial)
Diseases named in the same sentence as TFAM in open-access papers (continued):
Sharing a sentence is not in itself a finding about the gene and the disease.
endometrial cancer (2 papers, 2022 to 2023). Primary or metastatic malignant neoplasm involving the endometrium (mucous membrane that lines the endometrial cavity). "The expression of TFAM in endometrial cancer is associated with tumor invasion and metastasis, including lymph node and distant metastasis, and TNM stage advancement." (PMID 37627097, 2023).
injury (2 papers, 2023 to 2025). Damage inflicted on the body as the direct or indirect result of an external force, with or without disruption of structural continuity. "Mitochondrial DAMPs (mtDAMPs) mainly include mitochondrial DNA (mtDNA), mitochondrial formyl peptides (mtFPs), mitochondrial transcription factor A (TFAM), cardiolipin (CL), ATP, cytochrome c, and mitochondrial RNA (mtRNA), which are also related to trauma-induced SIRS." (PMID 37533869, 2023).
Intellectual disability (2 papers, 2023 to 2024). "Furthermore, homozygous missense variants in TFAM have been reported in POI patients presenting with primary amenorrhea, atrophic ovaries, seizures, intellectual disability as well as clinical features of Perrault syndrome." (PMID 37148394, 2023).
kidney failure (2 papers, 2022). An acute or chronic condition that is characterized by the inability of the kidneys to adequately filter the blood. "However, no significant IRF3 activation was observed in TFAM mutant mice, and the STING-dependent NF-kB inflammatory signaling seems to play a promoting role in TFAM-deficiency-induced kidney failure and fibrosis." (PMID 35186921, 2022).
kidney injury (2 papers, 2023 to 2025). Trauma to the kidney. "Targeting C/EBPβ and TFAM to modulate inflammatory responses is a potentially viable intervention strategy to address As-induced kidney injury." (PMID 37624173, 2023). "For example, the acetylation of mitochondrial transcription factor A (TFAM) by GCN5L1 impairs its translocation to mitochondria, reducing mtDNA replication and transcription and exacerbating kidney injury." (PMID 40497970, 2025).
leprosy (2 papers, 2022 to 2025). Leprosy is a chronic infectious disease affecting primarily the skin and peripheral nervous system. "Mutations in genes like PARK2, which encodes the mitophagy factor Parkin, TFAM, which encodes a histone-like protein of the mitochondrial genome, as well as POLG, have been linked to leprosy susceptibility or severity of disease." (PMID 39969190, 2025). "Regardless, mutations in factors necessary to replicate and maintain the mitochondrial genome, with mutations in TFAM, the mitochondrial transcription factor A, and POLG, the mitochondrial DNA polymerase, are also associated with mycobacterial susceptibility and leprosy." (PMID 36076909, 2022).
liver disease (2 papers, 2020 to 2024). "Their data suggest that pathogenic TFAM variants and consequently, defects in mtDNA maintenance can be fatal (early-onset liver disease) and cause some rare genetic disorders, like Perrault syndrome." (PMID 32649732, 2020). "Variations in TFAM expression have also been observed in studies of other liver diseases." (PMID 38476236, 2024).
lung adenocarcinoma (2 papers, 2012 to 2019). A carcinoma that arises from the lung and is characterized by the presence of malignant glandular epithelial cells. "Previous reports have shown that the expression of TFAM was up-regulated, together with the increase of the mtDNA copy number after α-particle irradiation in human lung adenocarcinoma A549 cells." (PMID 30862036, 2019). "Estradiol has been reported to increase mtDNA content in breast and lung adenocarcinoma cells that directly stimulate NRF-1 gene expression and increase TFAM expression, mitochondrial transcription and oxygen consumption." (PMID 22676897, 2012).
oral cancer (2 papers, 2014 to 2021). "Similarly, 24 and 72 h POMx treatment inhibits mRNA and protein expressions for mitochondrial biogenesis of gene expression (TFB2M, TFAM, POLRMT, and TUFM) in oral cancer cells." (PMID 34356350, 2021).
prostate carcinoma (2 papers, 2020 to 2022). A carcinoma that arises from epithelial cells of the prostate gland. "In some cases (e.g., liver in extrahepatic cholestasis and hepatocellular carcinoma, melanoma cell lines, or prostatic cancer cell lines treated with arsenic), compromised levels of TFAM may result in mtDNA mutations or deletions." (PMID 32824374, 2020).
sarcoma (2 papers, 2023 to 2024). A usually aggressive malignant neoplasm of the soft tissue or bone. "Specifically, c‐Myc colocalizes with nuclear FBP2 at the TFAM binding site, leading to the inhibition of TFAM expression and, consequently, sarcoma tumorigenesis." (PMID 38034101, 2023). "In addition to small molecule compounds that modulate the expression of TFAM, the oncogene c-Myc promotes nuclear transcription of TFAM, facilitating sarcoma growth, while Fructose-1,6-Bisphosphatase 2 (FBP2) overexpression inhibits c-Myc-mediated transcriptional regulation of TFAM." (PMID 38589371, 2024).
tauopathies (2 papers, 2024 to 2025). "Taken together, our study revealed that irisin mitigated microglial senescence via TFAM-driven mitochondrial biogenesis, suggesting a promising new avenue for therapeutic strategies targeting tauopathies." (PMID 38745313, 2024). "However, to the best of our knowledge, there is limited research on TFAM protein levels and the therapeutic role of TFAM overexpression in tauopathies." (PMID 38745313, 2024).
acute liver failure (1 paper, 2018). Rapid deterioration of liver function causing encephalopathy and coagulopathy. "During acute liver failure induced by LPS/D-GalN, CO induced the levels of mitochondrial PINK1 and Parkin, and PGC1α-mediated NRF1 and TFAM gene expressions, which could lead to promotion of mitochondrial turnover and biogenesis." (PMID 30333475, 2018).
amyloidosis (1 paper, 2025). A disorder characterized by the localized or diffuse accumulation of amyloid protein in various anatomic sites. "It has been shown that expression of PGC-1α and TFAM is decreased in individuals with AD and in animal models of amyloidosis compared to healthy individuals." (PMID 41463129, 2025).
bacterial sepsis (1 paper, 2025). "Furthermore, despite the notable differences between bacterial sepsis and COVID-19, such as the immune response, we have been able to illuminate key shared pathophysiological mechanisms, for instance mitochondrial dysfunction and potential mislocalization of TFAM, underlying both conditions." (PMID 40458415, 2025).
Bloom syndrome (1 paper, 2021). Bloom syndrome (BSyn) is a rare chromosomal breakage syndrome characterized by a marked genetic instability associated with pre- and postnatal growth retardation, facial sun-sensitive telangiectatic erythema, increased susceptibility to infections, and predisposition to cancer. "Upregulation of TFAM is a characteristic marker of many different cancer tissues and is associated with malignant progression and poor prognosis, raising the possibility that it also contributes to cancer risk in Bloom syndrome." (PMID 33495511, 2021). "In this study, we have identified abnormalities in Bloom-syndrome-patient-derived cells and BLM-knockout cells that include increased ROS that causes DNA base damage and reduced DNA replication speed, increased mitochondrial mass and TFAM expression, and mitochondrial fragmentation." (PMID 33495511, 2021). "TFAM was upregulated fourfold in KSVS1452 (BLMKO) cells and 2.5-fold in Bloom- syndrome-patient-derived GM08505 (BLM−/−) cells, consistent with increased mitochondrial mass in these cells." (PMID 33495511, 2021).
clear cell renal cell carcinoma (1 paper, 2020). "In clear cell renal cell carcinoma, the ability of TFAM to interact with mtDNA is impaired when it is acetylated at Lys-154 and therefore the protein deacetylase SIRT3 regulates the TFAM function and mitochondrial biogenesis." (PMID 32824374, 2020).
contact dermatitis (1 paper, 2021). An inflammatory skin condition caused by direct contact between the skin and either an irritating substance or an allergen. "Finally, we examined whether ectopic TFAM expression could recover impaired T-cell function in SATB1cKO mice in vivo by the picryl chloride (PCI) contact dermatitis model." (PMID 34583974, 2021).
Crohn disease (1 paper, 2020). A gastrointestinal disorder characterized by chronic inflammation involving all layers of the intestinal wall, noncaseating granulomas affecting the intestinal wall and regional lymph nodes, and transmural fibrosis. "Thus, a combination of TFAM with si-Smad or MAPK inhibitors had greater inhibitory effects on the TGF-β1-induced epithelial–mesenchymal transition in IEC-6 cells, which suggests that TFAM might represent a novel therapeutic strategy for the treatment of intestinal fibrosis in Crohn’s disease." (PMID 32973492, 2020).
dementia (1 paper, 2022). Loss of intellectual abilities interfering with an individual's social and occupational functions. "For example, there is a possibility that there are ethnic differences in polymorphisms in TFAM (mitochondrial transcription factor A), which encodes a key activator of mitochondrial transcription and is known to be related to the earlier onset of dementia among patients with Down syndrome." (PMID 34622557, 2022).
dengue (1 paper, 2022). "We observe that dengue downregulated NRF2 expression during the course of infection with a concomitant downregulation in the expression of TFAM." (PMID 36197108, 2022). "Confocal microscopy of dengue-infected cells further validated the gradual decline in TFAM levels resulting in a decline in the TFAM:TOMM20 ratio during the course of infection." (PMID 36197108, 2022). "We observed that dengue downregulated the expression of PPARγ and its coactivator PGC1α and also downregulated the expression of NRF2 and TFAM." (PMID 36197108, 2022).
diabetic retinopathy (1 paper, 2021). "The translocation of TFAM, which activates transcription of mtDNA, into the mitochondria is impaired in rats with diabetic retinopathy." (PMID 33491664, 2021).
dysplasia (1 paper, 2017). A usually neoplastic transformation of the cell, associated with altered architectural tissue patterns. "Remarkably, up-regulation of POLG and TFAM in 12 months H. pylori SS1-infected INS-GAS mice occurred in parallel with exacerbation of the severity of gastric lesions, namely dysplasia and GIN development." (PMID 29162845, 2017).
endotoxemia (1 paper, 2020). "Thus, the timely (within the first 24 h) increases in cellular TFAM expression in PBMCs of septic patients and in endotoxemia, as supported by our results, may be beneficial and promote mitochondrial recovery." (PMID 33273525, 2020).
gastric adenocarcinoma (1 paper, 2025).
HCMV infection (1 paper, 2022). "In addition, the genes relate to mitochondrial biogenesis (PGC-1α, TFAM, and NRF1) and oxidative phosphorylation (ATP5G1 and Cox5a) were also decreased after HCMV infection." (PMID 35359726, 2022).
Herpes simplex infection (1 paper, 2021). "Consistently, Herpes simplex infection, influenza A, measles, cytokine-cytokine receptor interaction and Toll-like receptor signaling pathway were the top five enriched KEGG pathways by TFAM down-regulated genes, which included three viruses and two viral response pathways." (PMID 34876009, 2021).
herpesvirus infection (1 paper, 2016). "A recent study has showed that mitochondrial transcription factor A (TFAM) depletion, induced genetically or during herpesvirus infection, triggers disruption of mtDNA stability, which is characterized by nucleoid loss and enlargement." (PMID 26498951, 2016).
Hutchinson-Gilford progeria syndrome (1 paper, 2021). "The authors also showed that enlarged phase-separated mitochondrial nucleoids could be observed in the premature ageing disease Hutchinson-Gilford Progeria Syndrome (HGPS) in association with TFAM and that this is linked to impaired mitochondrial oxidative phosphorylation and ATP regeneration." (PMID 34392401, 2021).
hyperthyroidism (1 paper, 2025). Overactivity of the thyroid gland resulting in overproduction of thyroid hormone and increased metabolic rate. "However, despite activation of the upstream regulator NRF1, the level of TFAM protein, which is the final effector directly responsible for mitochondrial DNA replication and transcription, reduced in hyperthyroidism." (PMID 41369368, 2025).
iron deficiency (1 paper, 2016). "The abundance of TFAM, PGC1‐α, and PGC1‐β mRNAs in the fetal livers on d21.5 of gestation was unaffected by iron deficiency (data not shown)." (PMID 27905292, 2016).
ischemia reperfusion injury (1 paper, 2025). Adverse functional, metabolic, or structural changes in ischemic tissues resulting from the restoration of blood flow to the tissue (reperfusion), including swelling; hemorrhage; necrosis; and damage from free radicals. "Additionally, in ischemia-reperfusion injury-induced acute kidney injury (IRI-AKI), mitochondrial ROS not only aggravate necrosis but also impair mtDNA integrity by disrupting mitochondrial Mitochondrial Transcription Factor A (TFAM) activity, sustaining chronic inflammation." (PMID 41142308, 2025).
ischemic heart disease (1 paper, 2024). "Proteins involved in mitochondrial biogenesis such as PGC-1α, AKT, TFAM and Sirtuin are reduced in ischemic heart disease, while exercise training upregulates PGC-1α, AKT, and (TFAM) level in diabetic hearts." (PMID 39795867, 2024).
lactic acidosis (1 paper, 2019). Metabolic acidosis characterized by the accumulation of lactate in the body. "A-549 and MCF-7 cells increased levels of NRF-1, NRF-2, and TFAM with respect to MRC-5 cells, whereas A-427 cells upregulated these transcripts under lactic acidosis compared with neutral lactosis." (PMID 31681589, 2019). "Although some tumor cell lines (A-549 and MCF-7) maintained increased levels of NRF-1, NRF-2 and TFAM, lactic acidosis promoted the increase in NRF-1, NRF-2, and TFAM transcript levels, only when the tumor cells expressed low levels of the transcription factors." (PMID 31681589, 2019). "In contrast, MRC-5 cells cultured under lactic acidosis did not increase the NRF-1, NRF-2, and TFAM transcript levels." (PMID 31681589, 2019).
leukemia (1 paper, 2024). A malignant (clonal) hematologic disorder, involving hematopoietic stem cells and characterized by the presence of primitive or atypical myeloid or lymphoid cells in the bone marrow and the blood. "In this regard, our innovative approach of enhancing T-cells’ nutrient competency and metabolism through genetic overexpression of GLUT1 and TFAM aims to address the metabolic competition of CAR T cells against blasts in the leukemia-controlled microenvironment." (PMID 39457563, 2024).
lymphoma (1 paper, 2023). A malignant (clonal) proliferation of B- lymphocytes or T- lymphocytes which involves the lymph nodes, bone marrow and/or extranodal sites. "We found very markedly higher expression of COXI in transferred lymphoma cells compared with WT B cells, with significantly upregulated TFAM." (PMID 37095377, 2023). "We also demonstrate, using genetically modified mouse models, that TFAM is essential for the development of lymphoma and that pharmacological inhibition of mitochondrial transcription and translation in human lymphoma cells is a potential treatment target for human disease." (PMID 37095377, 2023). "Having demonstrated an essential role for TFAM in B cell development and entry into the GC, we next asked whether it was required for the development of lymphoma." (PMID 37095377, 2023).
malignant fibrous histiocytoma (1 paper, 2014). "We have also shown that, in human malignant fibrous histiocytoma (MFH) xenografts, transcutaneous CO2 decreases expression of HIF-1α and induces mitochondrial apoptosis, in turn increasing PGC-1α and mitochondrial transcription factor A (TFAM)." (PMID 24988190, 2014).
monoclonal gammopathies (1 paper, 2021). "To elucidate whether the increase in mtDNACN was correlated with the expression of mitochondrial biogenesis regulators, we measured the levels of TUFM and TFAM by quantitative PCR in the different states of monoclonal gammopathies." (PMID 34202390, 2021).
nasal polyp (1 paper, 2020). "Our finding showed that the expression of mitochondrial biogenesis markers such as NRF1, NRF2, TFAM, and COX4 was decreased in the epithelium of nasal polyp." (PMID 33598458, 2020). "Moreover, the decreased expression of NRF1, NRF2, TFAM, and COX4 was also observed in the nasal epithelium and nasal polyps by immunohistochemical staining." (PMID 33598458, 2020).
osteoarthritis (1 paper, 2020). A noninflammatory degenerative joint disease occurring chiefly in older persons, characterized by degeneration of the articular cartilage, hypertrophy of bone at the margins and changes in the synovial membrane. "Specifically, in a study to develop a therapeutic strategy for osteoarthritis, Que was shown to increase expression levels of SIRT1, PGC-1α, NRF1 and NFR2, TFAM, and phospho-AMPK α in osteoarthritis rats, confirming the hypothesis that Que might act via the AMPK/SIRT1 signaling pathway." (PMID 32848804, 2020).
osteonecrosis (1 paper, 2020). A none disease characterized by death of bone tissue due to a lack of blood supply. "Regarding mitochondria, which are the major site of oxidative stress generation, the intraosseous decrease of their TFAM levels induced by glucocorticoid administration has been implicated in osteonecrosis development, suggesting that mitochondrial stress plays a role in this process." (PMID 32962196, 2020). "On the other hand, in the MP+/TAU+ group, similar to the in vitro results, TFAM and ATP5A showed improvement up to the levels seen in MP−/TAU− group, as well as a significant decrease in the incidence of osteonecrosis." (PMID 32962196, 2020).
ovarian clear cell cancer (1 paper, 2017). An invasive malignant neoplasm that arises from the ovary and is characterized by a predominance of clear and hobnail malignant epithelial cells. "The data for TFAM are also consistent with data from other researchers who show that TFAM and PGC1α levels are reduced in the acquired cisplatin resistant ovarian clear-cell carcinoma subline SKOV-3-R when compared to parental controls." (PMID 29212260, 2017).
Peritoneal Fibrosis (1 paper, 2022). Disorder characterized by a wide range of structural changes in PERITONEUM, resulting from fibrogenic or inflammatory processes. "In this study, we observed the downregulation of PGC-1α signaling, which was manifested by decreased protein expression of PGC-1α, NRF-1, NRF-2 and TFAM and PGC-1α mRNA expression in high glucose-based PD fluid-induced peritoneal fibrosis." (PMID 36148521, 2022).
preeclampsia (1 paper, 2017). Preeclampsia is a hypertensive disorder of pregnancy that is characterized by new-onset hypertension with proteinuria presenting after 20 weeks of gestation, and depending on mild or severe forms may initially present with severe headache, visual disturbances, and hyperreflexia. "In late-onset preeclampsia, expression levels of essential mitochondria-related proteins VDAC1, TFAM, hexokinase 1, PGC-1α and PGC-1β, and autophagy marker LC3A, were significantly elevated." (PMID 28736722, 2017).
Premature ovarian insufficiency (1 paper, 2021). Amenorrhea due to loss of ovarian function before the age of 40. "A recessive TFAM variant report in primary ovarian insufficiency showed that the depletion of TFAM can alter mitochondrial function and morphology." (PMID 35054416, 2021).